BDNF (brain derived neurotrophic factor)
Diseases named in the same sentence as BDNF in open-access papers (continued):
Sharing a sentence is not in itself a finding about the gene and the disease.
depression (continued). "This fits with evidence from others suggesting that BDNF is negatively correlated with depression as well as emotional exhaustion and depersonalization and increases in association with successful treatment of depression." (PMID 28694775, 2017). "Therefore, the present study aimed to determine the effect of ginseng extract G115 in ethanol-induced depression mice and its underlying antidepressant mechanisms involving BDNF levels in the brain." (PMID 28837087, 2017). "This is consistent with recent research that has found an association between the BDNF gene Val66Met polymorphism, rumination, and depression, where analyses suggested that rumination mediated the relationship between the BDNF polymorphism and depressive symptoms." (PMID 27352637, 2016). "Our findings supported our hypotheses, providing important insight into the lifetime when EET is most effective against depression caused by BDNF deficiency." (PMID 27648918, 2016). "Thus it seems that abnormal BDNF levels in the VTA–NAc pathways play a causative role in the pathophysiology of depression." (PMID 27821848, 2016). "The identification of molecular targets that can enhance BDNF signaling in the mPFC may reveal the mechanisms underlying cognitive dysfunction and contribute to effective strategies to improve the treatment of depression." (PMID 27757074, 2016). "Several studies indicate promoter methylation of BDNF to be associated with major depression." (PMID 28096796, 2016). "Thus, it is likely that CUMS causes the reduction of BDNF in the hippocampus, followed decreased p11 expression, resulting in depression-like behavior in rats." (PMID 26905413, 2016). "BDNF has long been implicated as a potential marker of depression and antidepressant response." (PMID 27494716, 2016). "As discussed in the previous section, depression is consistently associated with depleted BDNF." (PMID 28082989, 2016). "On the other hand, the neurotrophin hypothesis of depression suggests that a decrease in neurotrophins, particularly BDNF, is an important cause of depression, and that anti-depressant drugs exert their effects by increasing BDNF levels." (PMID 27120588, 2016). "However, it remains to be revealed how BDNF methylation-associated occipital cortical thinning contributes to the symptoms of depression." (PMID 26876488, 2016). "Importantly, miR-182 overexpression was found to be associated with depression-like behaviours and decreased hippocampal BDNF expression in stressed rats, and miR-182 silencing led to anti-depressant-like effects." (PMID 27883060, 2016). "Moreover BDNF gene (Val66Met polymorphism) was shown to be a strong risk factor for developing major depression." (PMID 27642354, 2016). "Hypermethylation or hypomethylation of key genes for the development of depression in men, such as the AR, BDNF, 5HTT, FKBP5, and NR3C1 constitute independent risk and resilience factors for depression, AUDs, and suicidal behavior and further interact with the prior described genetic predisposition." (PMID 28096796, 2016). "It is also possible that loss of BDNF in conditional knockouts is insufficient to cause depression-like behavior, but is prone to do so when BDNF levels are further reduced by inactive promoter IV under stress, and females may be more susceptible to stress." (PMID 27648918, 2016). "Notably, the Met allele of BDNF, Val66Met, has been shown to have significant associations with life stress and depression." (PMID 26445699, 2015). "Recently, riluzole has been proposed for the treatment of depression because it has the ability to lower extracellular glutamate levels and increase BDNF expression; and both mechanisms could be associated with its antidepressant action." (PMID 25629040, 2015). "A clinical meta-analysis showed that BDNF levels were associated with changes in depression." (PMID 26191079, 2015).
depression (continued). "Altered levels of BDNF may be responsible for the cognitive deficits and altered brain structure associated with depression, stress, and suicide." (PMID 25908105, 2015). "Although the mechanism of the effect of TrkB polymorphisms on the risk of PSD remains unknown, numerous investigators have shown that BDNF is associated with the pathogenesis of depression, including PSD." (PMID 26641254, 2015). "Lower BDNF levels were associated with increased odds of maternal antepartum depression." (PMID 25886523, 2015). "As opposed to limiting investigations to a single gene, further studies examining net effects of BDNF and serotonin-related polymorphisms may better explain stress-associated depression risk factors." (PMID 25781924, 2015). "However, a valine (Val) to methionine (Met) substitution at nucleotide 66 (Val66Met; refSNP: rs6265) in the BDNF gene influences risk of depression in older adults." (PMID 25781924, 2015). "For this section, we will initiate discussion of the molecular pathologies by examining the hypothesized role of genetic polymorphisms with established associations with depression (e.g., dopamine D2 receptor, GR, and BDNF)." (PMID 25806005, 2015). "In addition, a functional study found increased hippocampal activity during processing of emotional facial expressions in adolescents suffering from depression who also carried the BDNF Met allele." (PMID 26230319, 2015). "Lower maternal serum BDNF levels in early pregnancy are associated with antepartum depression." (PMID 25886523, 2015). "Similarly, alterations in BDNF methylation status have been associated with major depressive disorder, suicidal behavior and completed suicide as well as borderline personality disorder and related childhood abuse history." (PMID 26649946, 2015). "Previous results suggested that a lower level of BDNF expression is associated with depression." (PMID 26175754, 2015). "Furthermore, unlike previous studies, we included genetic variation across the BDNF gene as a potential modifier of the association between depression and methylation levels." (PMID 26285129, 2015). "It is hypothesized that pathological changes in BDNF levels are distally responsible for these neuropsychological deficits associated with depression, stress, and suicide." (PMID 26718989, 2015). "The involvement of genetic polymorphisms in the BDNF gene in peripheral tissues of patients with depression may reflect changes in the BDNF level in their brain." (PMID 26733829, 2015). "Medication may alter neurotrophic signalling; a number of studies have investigated the effect of antidepressants on peripheral BDNF levels in patients with depression and showed that the use of SSRIs is associated with an increase in peripheral BDNF levels." (PMID 26011424, 2015). "In a recent experiment, chronic social defeat stress or treatment with exogenous CORT caused a significant decrease in BDNF expression in the hippocampus, a brain region that may be related to the pathogenesis of depression-like symptoms." (PMID 26138544, 2015). "Our results demonstrate that the stressful stimulus followed by the peripheral immune challenge decreases the cortical expression of BDNF mRNA at 24 h after LPS and these findings are in agreement with several studies that used animal models of depression associated to inflammation." (PMID 26170871, 2015). "Three polymorphisms, including the widely investigated Val66Met (rs6265), were found to modify the association, such that for minor allele carriers of rs6265 and rs7103411 and major allele carriers of rs908867, depression was specifically associated with elevated BDNF methylation." (PMID 26285129, 2015). "Furthermore, chronic depression was also significantly associated with BDNF methylation at the same CpG sites, with associations being even stronger than with baseline depression." (PMID 26285129, 2015).
depression (continued). "Beyond this intriguing possibility for its use as a biomarker for depression it is postulated here that reduced levels of BDNF may also be a suitable prospective biomarker for CHD risk." (PMID 26231223, 2015). "Collectively, these studies in diverse animal models are consistent with the notion that reduction in BDNF levels may be causally related to depression and depressive symptoms." (PMID 25886523, 2015). "Stress-induced reductions of BDNF may produce a risk for depression, while restoration of HPA axis and BDNF homeostasis following E2 and Tualang honey treatment may be responsible for the improvement in mood." (PMID 24550703, 2014). "Moreover, IL-6 has been suggested to be associated with brain-derived neurotrophic factor (BDNF) which is highly involved in the physiopathology of depression." (PMID 24795767, 2014). "Moreover BDNF has been associated with various human diseases including depression, epilepsy, Alzheimer, Parkinson and Huntington, i.e. BDNF has been mainly studied as a growth factor in the central and peripheral nervous system." (PMID 25036590, 2014). "The results suggest that LPS-induced inflammation may cause depression-like behavior by altering BDNF and spine density in the CA3, DG, PFC, and NAc, which may be involved in the antidepressant effects of 7,8-DHF and ANA-12, respectively." (PMID 25628381, 2014). "Stress is hypothesised to cause a reduction in BDNF (protein) levels in the brain (particularly in regions linked to emotion), which alters mood and may cause depression." (PMID 24433458, 2014). "In addition, it has been reported that genetic variant of TrkB is also associated with the risk of depression, further suggesting that the importance of BDNF/TrkB system in brain function." (PMID 25309465, 2014). "The BDNF gene consists of a number of polymorphisms which may also be relevant for gene-environment interactions in depression." (PMID 24433458, 2014). "In particular, the neurotrophic factor BDNF (brain-derived neurotrophic factor), which is a part of the neurotrophin pathway, has been previously associated to Alzheimer's, Parkinson's disease and depression." (PMID 25211452, 2014). "Intense stress, such as that experienced during severe depression, can cause reduced expression of brain-derived neurotrophic factor (BDNF) in the hippocampus and elevated expression of cortisol, leading to decreased hippocampal neurogenesis and overall atrophy of the structure." (PMID 25338068, 2014). "Deficiency of brain-derived neurotrophic factor (BDNF) is involved in the mechanism of depression." (PMID 24524285, 2014). "BDNF has been reported to be associated with depression, and the severity of depression might be affected by changes in BDNF after antidepressant treatment." (PMID 24524285, 2014). "The purpose of the present work was to systematically review and perform a meta-analysis on studies that have investigated the interaction between the Val66Met polymorphism in the BDNF gene and life stress (childhood adversity and stressful life events) in depression." (PMID 24433458, 2014). "At the cellular and molecular levels, decreased levels of AHN and altered levels of BDNF have also been associated with increased anxiety and may possibly account for their high comorbid prevalence with depressive disorders." (PMID 24900924, 2014). "In line with prior research, we hypothesized that genetic prediction of depression risk (the association between BDNF and rumination) would be significantly stronger among adolescents." (PMID 24312122, 2013). "We therefore explored whether the BDNF Val66Met polymorphism is associated with co-morbid depression and whether depression affects the serum levels of BDNF in a Han Chinese subjects with T2DM." (PMID 23968401, 2013). "Most treatments against anxiety and depression are associated with the action of BDNF." (PMID 23483949, 2013).
depression (continued). "It has been postulated that the balance of TrkB and p75 signalling may underlie antidepressant effects of BDNF, suggesting a mechanism through which stress/depression may modulate the effects of BDNF." (PMID 23691371, 2013). "BDNF is the best studied neurotrophic factor implicated in depression." (PMID 23710213, 2013). "It was found that early life stress lowers BDNF and alters stress sensitivity later in life, whereas increases in BDNF, either via social enrichment or direct infusion into the brain, was found to reduce susceptibility to depression-like behavior." (PMID 23847583, 2013). "Our study provides further evidence that the BDNF Val66Met polymorphisms may be a good therapeutic candidate gene for T2DM patients with depression in Chinese subjects." (PMID 23968401, 2013). "The presence of inflammatory processes and endothelial dysfunction compromise the production and secretion of brain-derived neurotrophic factor (BDNF), a peptide implicated in synaptic plasticity and neuronal survival, and whose levels are decreased in patients with depression." (PMID 24229349, 2013). "There is study that suggests that depression in diabetes may disturb the balance of brain-derived neurotrophic factor (BDNF), causing cognitive decline or dementia." (PMID 24386004, 2013). "In the presence of the Met allele, however, reduced plasticity (related to low BDNF activity) might itself favor the emergence of depression, but it would also limit the damage that could otherwise be inflicted by adverse early life experiences." (PMID 23675319, 2013). "The BDNF Val66Met polymorphism might be implicated in the pathogenesis of depression in T2DM by decreasing serum BDNF levels in Han Chinese Subjects." (PMID 23968401, 2013). "Lastly, with a recent meta-analysis suggesting sex differences in the link between BDNF and depression risk we also tested whether sex would moderate the association." (PMID 24312122, 2013). "However, among those individuals homozygous for both the BDNF Val and the 5-HTTLPR long (l) alleles, marked plasma BDNF reductions and increased susceptibility to depression were evident in association with early life adversity." (PMID 23675319, 2013). "Indeed the findings concerning the relationship between BDNF polymorphisms and depression have been inconsistent, and the suggestion had been made that the link between BDNF and psychopathology ought to be re-evaluated." (PMID 23824678, 2013). "Taken together, our results suggest that prenatal exposure to supra-therapeutic dose of buprenorphine might result in depression-like phenotypes associated with decreased BDNF action in weanlings." (PMID 24367510, 2013). "In addition, the association between the low BDNF levels and the anhedonic profile, indicative of a depression-like phenotype, is in line with studies in patients." (PMID 23653679, 2013). "Next, although the study successfully replicated the association between the Val66Met SNP and rumination in adolescents, a more thorough analysis may incorporate haplotypes to further clarify the link between BDNF and depression risk." (PMID 24312122, 2013). "The loss of BDNF and TrkB could probably induce hippocampal neuronal atrophy and apoptosis, promoting depression, and may thus be a major pathogenesis of this disease." (PMID 24367385, 2013). "Differences between our study and previous study findings of an association between the BDNF Val66Met polymorphism and depression may be due to ethnic variances and alternative definitions for depression." (PMID 23968401, 2013). "Moreover, variants of the BDNF gene are linked with risk of neuropsychiatric disorders, including depression, eating disorders and schizophrenia." (PMID 23503168, 2013). "As antidepressants have been shown to reverse stress and depression induced BDNF downregulation and impaired neurogenesis, BDNF has been implicated in recovery mechanisms from depression, which resulted in the neurotrophin hypothesis of depression." (PMID 23750220, 2013).
depression (continued). "The gender-related influence of the BDNF Val66Met polymorphism in depression may be due to sexual dimorphism in brain structures involved in the neurobiology of depression, particularly, the hippocampus." (PMID 23968401, 2013). "We hypothesized to find a gene-by-environment, and possibly gene-by-gene-by-environment interaction on depressive symptoms, including the genetic polymorphisms 5-HTTLPR and BDNF Val66Met, traumatic life events and maternal symptoms of depression." (PMID 23518193, 2013). "Similarly to 5-HTTLPR, studies regarding the association between BDNF Val66Met and depression have been both confirmative and negating." (PMID 23518193, 2013). "It has been shown that a decreased BDNF expression underlies the stress and depression and, conversely, the use of antidepressants causes enhanced BDNF expression that could mediate the beneficial effects in the hippocampus and prefrontal cortex." (PMID 24348327, 2013). "The hypotheses that loss of BDNF and downstream diminution of brain growth manifests as depression and conversely that increasing BDNF prevents depression have been investigated." (PMID 22912626, 2012). "Thus, BDNF plays a pivotal role in the molecular pathways involved in depression, as well as in the mechanisms underlying antidepressant activity." (PMID 22581450, 2012). "The antidepressant effect of direct infusion of BDNF into rodent hippocampus and its blockade in knockout animals without the gene that encodes this factor in prosencephalic regions, provide more direct proof of its causal participation in depression." (PMID 23204984, 2012). "BDNF rs6265 polymorphism is linked to substantial reduction in the volume of hippocampus, a brain structure repeatedly associated with the treatment response and neurogenesis in depression." (PMID 22194899, 2011). "However, several lines of evidence suggest that lower active A allele of BDNF rs6265 polymorphism is associated with the features associated with the risk of depression." (PMID 22194899, 2011). "It not surprising therefore that it has been associated with a number of disorders of the brain, including Alzheimer’s disease, Huntington's disease, depression schizophrenia and Rett syndrome; with changes in BDNF levels being associated with each of these conditions." (PMID 22654716, 2011). "Animal studies indicate that decreased brain DHA in postpartum females leads to several depression-associated neurobiological changes including decreased hippocampal brain-derived neurotrophic factor and augmented hypothalamic-pituitary-adrenal responses to stress." (PMID 21151517, 2011). "Thus, due to the essential role of BDNF for cell differentiation, nerve growth and neuronal survival it has been implicated in several brain diseases, including depression." (PMID 22654714, 2011). "Decreased expression of BDNF in the hippocampus, a component of the limbic system involved in memory, affect, and regulation of the hypothalamic-pituitary-adrenal axis, is strongly implicated in the pathophysiology of depression." (PMID 21151517, 2011). "It has been suggested that stress and altered monoamine, hypothalamic-pituitary-adrenal (HPA) axis, brain-derived neurotrophic factor (BDNF), and glutamatergic neurotransmission might be implicated in the pathogenesis of major depression." (PMID 21698062, 2011). "Brain-derived neurotrophic factor (BDNF) is a neuroprotective protein which alters the balance of neurotoxic and neuroprotective responses to stress by preventing hippocampal cells from damage and is suggested to be associated with depression." (PMID 21494644, 2011). "However there is some discrepancy among different studies concerning the association between the Val66Met BDNF polymorphism and reduced hippocampal volumes in major depression." (PMID 22654714, 2011). "Several data lead to the hypothesis that BDNF deficiency might be one of the bridges between AD and major depression." (PMID 22654714, 2011).